AFP (alpha fetoprotein)
Diseases named in the same sentence as AFP in open-access papers (continued):
Sharing a sentence is not in itself a finding about the gene and the disease.
tumor (continued). "Our results revealed that co-index of HOXC6 expression and serum AFP level could be more beneficial for differentiating the risk of tumor survival and relapse of patients than HOXC6 expression or serum AFP alone." (PMID 29348394, 2018). "Furthermore, ITGA9 protein level associated well with alpha-fetoprotein, vascular invasion, tumor thrombosis, tumor size, and TNM stage." (PMID 29951557, 2018). "Similar to other cohorts, the findingsin the present study also indicate that elevated AFP is significantly associatedwith more aggressive tumor characteristics and poor clinical outcome, as well asgene expression related to cell cycle progression, DNA damage response, and MYConcogene pathways." (PMID 29376136, 2018). "In addition, both logistic regression analysis and ROC curve method showed that siglec-2 down-regulation in tumor tissues was significantly associated with AFP elevation over 300 ng/ml (P < 0.05)." (PMID 30355653, 2018). "Interestingly, 71.4% of HCC patients with AFP levels below 20 ng/mL showed loss of heterozygosity in the microsatellite regions, suggesting that this factor is an early marker of tumour development." (PMID 29597259, 2018). "The serum AFP level of patients with AFPGC was significantly associated with tumor differentiation." (PMID 28423604, 2017). "According to the results of univariable analyses, the Milan criteria (p < 0.001), the UCSF criteria (p < 0.001), the up-to-7 criteria (p < 0.001), and the last pretransplant AFP (p < 0.001) were significantly associated with the risk of posttransplant tumor recurrence." (PMID 27531306, 2017). "For these patients, although MVI increased the risk of tumor recurrence but other factors, e.g., AFP and γ-GT, may undermine its contribution to the long-term survival." (PMID 28095820, 2017). "This study clarified that rs1800734 was correlated with tumor size, tumor grade and AFP level, indicating that gene polymorphisms may cause carcinogenesis and different clinical-pathological features of patients." (PMID 29108386, 2017). "Recent studies have shown serum levels of AFP to be associated with tumor diameter, as did our data (r = 0.261, P = 0.035), with 58 (89.2%) patients having a tumor diameter >5 cm and 34 (52.3%) patients having a tumor diameter ≥10 cm." (PMID 28397025, 2017). "Therefore, AFP cutoff of 100 ng/ml is used in fact as an exclusion criterion, to bring the risk of tumor recurrence associated with increasing tumor burden to or below the level provided by the Milan criteria." (PMID 27531306, 2017). "In addition, older patients had an increased risk of recurrence, whereas younger patients with low AFP level and tumor size > 5 cm had a higher risk of death." (PMID 28418898, 2017). "Many other models were designed by introducing appropriate biomarkers such as serum AFP, HBsAg, cytoskeleton-associated protein 2, plasma fibrinogen which showed improved prognostic power for tumor recurrence and provided a wider perspective to consider for RR indication." (PMID 28968990, 2017). "Interestingly, miR-4651 had higher accuracy and sensitivity to identify small liver cancer and early-stage AFB1-positive HCC compared with AFP; highlighting its diagnostic value in AFP-negative tumor cases." (PMID 29113383, 2017). "Of the 7 clinical factors analyzed by Cox regression model, univariate analysis identified extrahepatic metastasis associated with TTR and 3 significant factors associated with survival, including AFP (P < 0.001), diameter of tumor (P = 0.044), and extrahepatic metastasis (P = 0.024)." (PMID 28623296, 2017). "However, neither of other clinicopathological features, including age, sex, serum AFP, and tumor number, was associated with B7-H4 expression." (PMID 29235470, 2017).
tumor (continued). "Furthermore, lower expression of hsa_circ_0004018 was associated with serum AFP level, tumor diameters, differentiation, BCLC stage and TNM stage." (PMID 28938566, 2017). "Furthermore, when the patient concomitantly had high AFP, which is a risk factor for tumor malignancy, we should attribute the symptoms to a single disease: HCC." (PMID 29390333, 2017). "Recently, studies have demonstrated several risk or predicting factors for PVI, such as tumor size, grade of differentiation, capsule formation, serum level of alpha fetoprotein (AFP), alkaline phosphatase (ALP) and platelet counts, by using univariable or multivariable analysis." (PMID 27793002, 2016). "CEA and AFP are both FDA approved as tumor-associated antigens." (PMID 26777057, 2016). "After analyzing the correlation between AKR1B10 mRNA expression in PHC tissues and the clinical data, we found that AKR1B10 mRNA expression was associated with serum alpha-fetoprotein (AFP), tumor-node-metastasis (TNM) stage, and lymph node metastasis, but not with other clinicopathologic variables." (PMID 26948042, 2016). "Multivariate Cox proportional hazards regression model revealed that Child-Pugh stage, tumor number, size of largest tumor, AFP and γ-GGT were independent risk factors of DFS, and tumor number, size of largest tumor, and γ-GGT were independent risk factors of OS." (PMID 27381639, 2016). "Factors such as general health, hepatic reserve, and tumor-associated factors such as vascular invasion and serum AFP levels predict the outcomes of patients with advanced HCC, and the progression pattern and cause of failure of sorafenib treatment stratifies patients’ outcomes." (PMID 27246496, 2016). "Tumor-derived AFP causes suppression of T lymphocyte responses." (PMID 28008329, 2016). "AFP was associated with vascular invasion (P <0.0001) and tumour number (P = 0.03)." (PMID 27219517, 2016). "Furthermore, tumor number, size of largest tumor, macro-vascular invasion, micro-vascular invasion, AFP and γ-GGT were significant risk factors associated with OS." (PMID 27381639, 2016). "Besides, serum AFP and vascular area/ tumor area were associated with OS, while tumor size was related with RFS." (PMID 26599011, 2015). "The high levels of AFP in this patient originally raised the question as to whether there was a tumor or another condition causing the expression of AFP." (PMID 25886790, 2015). "Although some recent studies have reported the association between AFP level and local tumor control or tumor response after SBRT, the significance of AFP normalization has yet not been studied in HCC patients after SBRT, which is an alternative ablative treatment used worldwide for small HCC." (PMID 26681337, 2015). "The ALDH1A1-high group was significantly associated with low serum levels of α-fetoprotein (AFP) (P = 0.0168), small tumor diameter (P = 0.0019), very little lymphovascular invasion (P = 0.0208), more differentiated pathology (P = 0.016) and good stage (P = 0.0215)." (PMID 26160842, 2015). "In the univariate analysis, AFP, γ-GT, tumor size, microvascular invasion, and tumor differentiation were associated with OS, whereas HBsAg, AFP, γ-GT, tumor size, microvascular invasion, tumor differentiation, and TNM stage were associated with cumulative recurrence." (PMID 25514599, 2015). "Tumor markers including AFP, β-hCG, and LDH are known to be associated with germ cell malignancy." (PMID 24731683, 2014). "The results indicated that the expression level of DPT in the HCC tissues was closely associated with vascular invasion (P = 0.005), tumor thrombosis (P = 0.003), tumor encapsulation (P = 0.013), tumor differentiation (P = 0.017), serum AFP (P = 0.016) and TNM stage (P = 0.047)." (PMID 25149533, 2014).
tumor (continued). "Based on the two-category classification (low/high H-score groups), the high H3K27me3 group correlated with poor differentiation, vascular invasion and serum alpha-fetoprotein (AFP) level, and the high H3K27ac group also had association with poor tumor differentiation." (PMID 24614346, 2014). "Univariate analysis identified the following prognostic risk factors in the total population: tumor number ≥3, serum AFP ≥400 ng/mL, serum albumin <4 g/dL, serum alanine aminotransferase >80 U/L, serum bilirubin >1.2 mg/dL, macrovascular invasion, major hepatectomy, and PHT." (PMID 25268959, 2014). "Downregulation of ANGPTL4 mRNA in HCC was significantly associated with advanced tumor stage, presence of venous infiltration, poor differentiation, higher AFP level, appearance of tumor recurrence, and poor postoperative overall and disease-free survivals of HCC patients." (PMID 25148701, 2014). "Moreover, combined AQP3 and AQP5 protein expression was significantly associated with serum AFP (P = 0.008), tumor stage (P = 0.006), and tumor grade (P = 0.006)." (PMID 24224160, 2013). "The detection of serum GP73 in combination with classic HCC tumor markers, AFP and GGT-II, may improve the diagnostic power for HCC." (PMID 24137480, 2013). "In addition, a high serum AFP level has been associated with larger tumor size, bilobar involvement, massive or diffuse-type tumors, and portal vein tumor thrombus." (PMID 23981851, 2013). "The results of statistical analysis indicated that low Fibulin-3 expression, defined by the receiver operating characteristic curve (ROC), was significantly associated with tumor differentiation (P = 0.008), clinical stage (P = 0.014) and serum AFP levels (P<0.01)." (PMID 23936443, 2013). "Meanwhile, low GPC3 staining combined with positive serum AFP may play a practical role in predicting poor postoperative outcome and high tumor recurrence risk." (PMID 23537217, 2013). "In addition, combined AQP3 and AQP5 protein expression was significantly associated with serum AFP (P = 0.008), tumor stage (P = 0.006), and tumor grade (P = 0.006)." (PMID 24224160, 2013). "In the present study, we found low expression of PLK4 in HCC was significantly associated with other malignant tumor characteristics, such as advanced stage and high serum AFP, indicating that PLK4 might be served as a hallmark of advanced stage tumors." (PMID 22829937, 2012). "Tumor differentiation, tumor encapsulation and AFP were associated only with OS." (PMID 22427881, 2012). "Factors associated with the presence of ME included pretreatment AFP level and tumor grade." (PMID 20731853, 2010). "In a simple Cox model, the endpoints were found to be significantly associated with tumor size, serum AFP levels of alpha fetoprotein (AFP), total albumin concentration (ALBU), venous infiltration (VENINV), tumor stage (pTNM and AJCC), and the number of tumor nodule (NOTN)." (PMID 19886989, 2009). "This may be due to the blood-borne dispersion of both tumor cells and normal liver cells during surgical manipulation and the mis-transcription of mRNA encoding AFP by peripheral mononuclear cells." (PMID 17244360, 2007). "AFP as a tumor-associated fetal protein has demonstrated clinical utility as a tumor marker." (PMID 16080799, 2005). "Notably, a increase in AFP levels exceeding 500 ng/ml has been linked with tumor size." (PMID 40575170, 2025). "This non-tumor increase might dilute the association between AFP and the malignancy of the tumor." (PMID 40936688, 2025). "In addition, a p.Pro925Ser mutation in PDGFRB, a receptor for PDGF correlated with alpha-fetoprotein, tumor size, and overall survival, was observed in the Oncopig HCC model 10 amino acids downstream (after accounting for homology) from a cBioPortal mutation that also formed a new Ser residue." (PMID 40340757, 2025).
tumor (continued). "Thus, even a short iRGD-induced spike in AFP transport from the tumour would be expected to cause elevated blood AFP levels for at least several hours, rendering it suitable to detect a potential iRGD-induced tumour-to-blood transport." (PMID 38889481, 2024). "Moreover, the 5-year overall survival rate of HCC was decreased by the high level of exosomal PDL1, and high level of exosomal PDL1 was significantly associated with the increased number of tumor nodules, the upregulated level of serum AFP, and the raised tendency of TNM stage." (PMID 39421264, 2024). "In addition, the presence of vessel invasion (HR, 1.480; 95% CI, 1.104–1.982; p = 0.009), extrahepatic metastasis (HR, 1.456; 95% CI, 1.092–1.940; p = 0.011), and AFP level > 200 ng/mL (HR, 1.395; 95% CI, 1.036–1.879; p = 0.028) were independent tumor-related risk factors for PFS." (PMID 38275895, 2024). "Increased values of alpha-fetoprotein can predict tumor recurrence following resection, the level of response to loco-regional therapy, the drop-out risk among patients awaiting liver transplantation (LT), as well as survival and tumor recurrence following LT, and survival in advanced HCC." (PMID 38611104, 2024). "Importantly, in the GSE14520 cohort, we noted that AFP (<=300 ng/ml), tumor size (<=5 cm) and non-multinodular were associated with the low-risk group, whereas AFP (>300 ng/ml), tumor size (>5 cm) and multinodular were mainly associated with the high-risk group (p < 0.05)." (PMID 36650832, 2023). "In addition, the RETREAT score (MVI, AFP, maximum tumor diameter, tumor count) assesses the risk of recurrence after transplantation and the AS score (age and international normalized ratio) assesses the risk of recurrence after liver resection and RFA have been documented." (PMID 37369911, 2023). "Therefore, AFP response to LRT was an alternative method for evaluating tumor aggressiveness and could be used to stratify the risk of tumor recurrence in HCC patients after LDLT." (PMID 36900345, 2023). "However, NETs may have better sensitivity and specificity for tumor diagnosis when combined with other tumor-associated markers such as AFP, CEA, and CA199, and their clinical utility should be validated in future studies." (PMID 35747797, 2022). "However, AFP obtained positive association in the mixed-type tumor (P = 0.041)." (PMID 36185222, 2022). "Since some paediatric malignancies are associated with the elevation of tumour markers, including alpha-fetoprotein (AFP), beta-human chorionic gonadotropin (βHCG), urinary catecholamine and certain hormones, a dedicated laboratory workup may help to establish the diagnosis." (PMID 35510137, 2022). "First, we performed univariate and multivariate Cox regression analyses of potential predictors, such as T stage, gender, age, residual tumour, histologic grade, AFP, vascular invasion, tumour status, and risk group, that may affect the prognosis of HCC patients." (PMID 35513781, 2022). "Additionally, AFP may be an important gene associated with the dissemination of primary HCC tumor cells." (PMID 35127471, 2021). "The selection of the specific cell line should be based on the aim of the respective study, e.g., whether cells are expected be derived from an Hepatitis B virus (HBV)-associated tumor, should be alpha-fetoprotein (AFP) positive, or need to express specific gene signatures." (PMID 32429417, 2020). "Samples in cluster-4 were associated with high AFP expression level, undifferentiated tumor cells and lymphatic metastasis while cluster-3 showed high incidence of distant metastasis; cluster-2 had a higher degree of vascular invasion and more tumor cells with low differentiation." (PMID 32887635, 2020). "Moreover, in TCGA cohort, correlation analysis between RACGAP1P expression and clinicopathological characteristics shown that high level of RACGAP1P in primary tumours was significantly associated with the advanced T stage, clinical stage and abnormal AFP level." (PMID 31160556, 2019).
tumor (continued). "Interestingly, a recent study showed that high expression of Pyk2 in peritumoral tissues was associated with poor survival, disease recurrence, and distant metastasis in HCC, and a higher Pyk2 density in both tumor and peritumoral tissues was associated with serum alpha-fetoprotein (AFP) levels." (PMID 29738483, 2018). "First, although AFP is not present at elevated levels in early-stage HCC and is thus a poor diagnostic biomarker, high serum AFP levels may reflect an increasing disease burden due to extrahepatic metastasis, advanced stage, large tumor size, and/or portal vein thrombosis." (PMID 29930697, 2018). "The aggressive biological features of AFP-producing GC are closely associated with abnormality of other tumor biomarkers and decrease of the proportion of peripheral lymphocytes, implying that post-operative increase of peripheral lymphocytes might benefit GC patients." (PMID 29254216, 2017). "Importantly, AFP expression in HCC tumor cells is associated with increased tumor proliferation, apoptosis resistance, and it is expressed in CD45-CD90+ putative HCC cancer stem cells, supporting its targeting as a biologically relevant tumor-associated antigen." (PMID 24708667, 2014). "Interestingly, the coexpression of GRB2 and GAB1 may be associated with serum AFP, tumor stage, tumor grade and patient prognosis." (PMID 24391994, 2013). "Hepatectomy should be judiciously selected for patients with AFP level > 1,000 ng/ml, tumor number ≥ 4, and tumor size ≥ 5 cm, because patients with these preoperative risk factors tend to die within 1 year after hepatectomy; these patients might be better treated with other therapy." (PMID 22697061, 2012). "Blood carcinoembryonic antigen (CEA) level was highly elevated at 127 ng/ml (normal < 5), while other tumor markers, including alpha-fetoprotein, β-human chorionic gonadotropin, and interleukin-2R levels, were normal." (PMID 41630024, 2026). "Cluster 6 differs from the other clusters by exhibiting the highest AFP levels, indicative of an aggressive tumor-driven profile." (PMID 41536859, 2026). "DC101 significantly inhibited tumor growth and disrupted cell–cell interactions between AFP-positive HCC cells and VEGFR2-positive endothelial cells (ECs) in human HCC xenograft models." (PMID 41140754, 2026). "Tumor markers related to HCC such as AFP, PIVKA 2, related to CCC such as CEA, CA19-9, and related to SCC such as cyfla were within normal limits." (PMID 41515615, 2026). "Traditional tumor markers such as AFP and PIVKA‐2 are also well‐known predictors of IDR, while elevated γ‐GT independently predicts both diminished survival and higher recurrence risk." (PMID 41499228, 2026). "Its accuracy in distinguishing HCC patients from healthy controls, chronic hepatitis B patients, and cirrhosis patients (AUC values of 0.863, 0.843, and 0.864, respectively) was significantly higher than that of the traditional tumor marker AFP." (PMID 41602547, 2026). "Independent prognostic factors for poor overall survival included albumin-bilirubin grade 2-3, alpha-fetoprotein ≥400 ng/mL, maximum tumor size ≥8 cm, presence of extrahepatic metastasis, and absence of conversion surgery." (PMID 42112317, 2026). "Stemness-associated genes such as GDF15, ALDH1L1, GPC3, AFP, EPCAM, CD44, and CD24 were predominantly expressed in tumor cells, with varying levels across other cell types including CAFs, TECs, and TAMs." (PMID 41493679, 2026). "Multivariate Cox analysis further determined that lymphocyte count, maximum tumor diameter, alpha fetoprotein level, number of tumor lesions, and portal vein invasion were independent risk factors." (PMID 42222382, 2026). "Elevated TUBB2A expression correlated with higher AFP levels, microvascular invasion, advanced tumor stages, and poorer overall survival." (PMID 41918784, 2026). "Traditional criteria based on tumor size, nodule number, and AFP levels have had limited success in predicting aggressiveness." (PMID 41749809, 2026).